BRAF (B-Raf proto-oncogene, serine/threonine kinase)
Diseases named in the same sentence as BRAF in open-access papers (continued):
Sharing a sentence is not in itself a finding about the gene and the disease.
melanoma (continued). "The IMspire150 study randomized 514 treatment-naïve patients with V600 BRAF mutated unresectable stage III/IV melanoma to treatment with vemurafenib and cobimetinib (V/C) plus or minus the PD-L1 inhibitor atezolizumab." (PMID 33435389, 2021). "In this study, based on the molecular characterization of the two divergent groups, we show a higher frequency of mutations in different genes in the CSD melanomas than in the nevogenic melanomas except for BRAF mutations." (PMID 34680367, 2021). "Aside from KRAS (colorectal cancer, amplified in 1% of TCGA cases), MCL1 (lung squamous carcinoma, 4.7%) and BRAF (melanoma, 4.1%) amplifications have also been implicated as oncogenic alterations in OncoKB." (PMID 34313788, 2021). "Almost half of all melanomas express a mutated form of the B-Raf proto-oncogene kinase (BRAF) and the majority of these are BRAF V600 mutations." (PMID 32291725, 2021). "Aside from one complete response in a BRAF-mutated melanoma patient with brain metastases, only 8 of 101 patients remained on the trial longer than five months." (PMID 33435389, 2021). "Previous reports confirmed the effectiveness of kinase inhibitors in human melanoma patients harboring BRAF V600E mutations." (PMID 34502061, 2021). "Subsequently, we investigated the transcriptional regulation of miR-129-5p downstream of constitutive active BRAF signaling and the biological function of miR-129-5p in BRAF mutated melanoma, as well as BRAFi resistance." (PMID 34063443, 2021). "83% (100/121) of melanoma cases had highly recurrent mutations in NRAS (27/121) or BRAF (n=73/121) that were mutually exclusive." (PMID 34804979, 2021). "In melanoma, vemurafenib was shown to improve the rates of response and overall survival of patients with the BRAF V600E mutation." (PMID 34207556, 2021). "It is estimated that about half of melanoma patients have mutations in BRAF, with BRAFV600E representing approximately 80% of these mutations." (PMID 34944799, 2021). "About 50% of malignant melanomas have a BRAF (V600E) mutation, while ExoDNA mutant alleles have been reported in mutant cell lines." (PMID 34234872, 2021). "BRAF mutation in melanoma cells results in constitutive activation of the MEK/ERK pathway and activation of MNK1/2." (PMID 33916175, 2021). "The BRAF V600E mutation is frequently detected in human cancer, especially thyroid carcinoma, melanoma, and non-small cell lung cancer but it is uncommon in urothelial carcinoma." (PMID 34502061, 2021). "Traditionally, the samples used for the detection of BRAF mutations in patients with melanoma, are formalin-fixed paraffin-embedded tissue biopsies." (PMID 34298804, 2021). "BRAF-mutated melanoma cells depleted of mitochondrial DNA show higher sensitivity to BRAF inhibitors, highlighting a key role of mitochondria in the development of resistance to MAPK pathway inhibitors." (PMID 33007949, 2020). "Taken together, these results suggest that the BRAF-mutated melanoma cells, including the isogenic subclones, under MAPKi treatment, tend to decrease both their glycolysis and OXPHOS activities and acquire a L/L state, while converging to an idling state." (PMID 32923395, 2020). "For patients with BRAF V600K-mutated melanoma, the mPFS were 8.1 and 15.9 weeks for cohort A and B, respectively." (PMID 32575838, 2020). "Mutations in PIK3CA were most frequently identified in breast cancers and lung cancers, while BRAF mutations were most frequently identified in colorectal cancers and melanomas." (PMID 32087721, 2020). "In cellular systems with BRAF-mutated melanoma cell lines when co-treated with phenformin (diabetes drug) and BRAF inhibitor (PLX4720) a decreased cell viability was registered." (PMID 32509589, 2020).
melanoma (continued). "Dacarbazine is a chemotherapeutic drug for metastatic melanoma and vemurafenib is a B-Raf enzyme inhibitor to treat late stage of melanoma with BRAF V600E mutation." (PMID 32085741, 2020). "Approximately 40% of patients with melanoma exhibit exon 15 BRAF mutations in cancer cells, resulting in constitutive activation of the mitogen-activated protein kinase (MAPK) cascade." (PMID 32784823, 2020). "Almost 50% of melanoma patients harbor a driver for a mutation found in the BRAF gene, therefore BRAF studies provide for a target-based therapy to control this disease." (PMID 33091721, 2020). "In BRAF-mutated melanoma, combination immunotherapy achieved similar response rates to those achieved by BRAF and MEK targeted combination therapy." (PMID 32517051, 2020). "The occurrence of BRAFV600+ mutation is associated with an increased pDC density in melanoma metastasis compared with BRAF wild-type tumors, whereas in locally advanced PCM, a collapse of the pDC compartment particularly occurs in NRAS-mutated tumors." (PMID 32731406, 2020). "Since the discovery of BRAF mutations in melanoma by Davies and colleagues in 2002, several studies have been performed to understand their association with different melanoma phenotypes and survival." (PMID 32393282, 2020). "Populations in Brazil, the US, Sweden, Italian, and Australia were found to be correlated to mutations of BRAF and melanoma." (PMID 31274706, 2020). "BRAF-mutant and PTEN-loss melanomas show, after an initial response to treatments, the development of resistance to BRAF inhibitors mediated by reactivation of MAPK and PI3K pathways." (PMID 33036192, 2020). "Since melanoma acquired resistance to BRAF inhibitors (BRAFi) has been associated with activation of pro‐angiogenic pathways, we have investigated VEGFR‐1 involvement in vemurafenib resistance." (PMID 31758648, 2020). "It constitutes about 90% of the BRAF mutations observed in melanoma and in almost 50% of melanoma patients." (PMID 32013263, 2020). "BRAF V600E oncogenic mutation is detected in lymph-derived melanoma EVs, and the increase in mutation frequency in patients correlates with risk of relapse." (PMID 31820036, 2020). "The patient with BRAF N581S melanoma (case DM077) was found to have two concurrent NRAS mutations (Q61K, Q61R) and initially demonstrated a partial response to treatment, but again progressed quickly after 4 months." (PMID 31839677, 2020). "The vemurafenib‐resistant A375‐VR and M14‐VR melanoma cell lines were generated by chronic exposure of A375 and M14 cells, which harbour the BRAF V600E mutation and are susceptible to BRAFi,31 to increasing concentrations of vemurafenib." (PMID 31758648, 2020). "As the current literature concerning metabolic changes in resistant melanoma cells mainly focuses on BRAF mutated cells, we decided to expand our studies to other important mutational profiles." (PMID 32455924, 2020). "As a result, BRAF inhibitor-resistant melanoma was susceptible to complex I inhibition with phenformin, which re-sensitised cells to BRAF inhibition." (PMID 33092283, 2020). "This study provides insight into the real‐world treatment landscape for advanced melanoma and suggests that receipt of 1L aPD‐1 is associated with favorable outcomes among patients with BRAF‐mutant advanced melanoma." (PMID 32871054, 2020). "In humans, approximately 50% of patients with melanoma have the BRAF V600E mutation, and BRAF-mutated ctDNA levels have been shown to serve as specific biomarkers in these patients." (PMID 32330187, 2020). "Although the use of BRAF/MEK inhibitors is essential to BRAF mutations therapy, it lacks efficacy in BRAF WT melanoma." (PMID 33392197, 2020). "For > 50% of all melanomas and melanocytic nevi, the BRAF mutation with constitutive downstream activation has been reported." (PMID 32213878, 2020). "In summary, our analyses suggest that L/L phenotype is clinically relevant in BRAF-mutated melanomas." (PMID 32923395, 2020).
melanoma (continued). "Most of the seminal work was done in metastatic malignant melanoma, which is hallmarked by a high prevalence of BRAF (50–60%) and NRAS (15–20%) mutations." (PMID 32046099, 2020). "Asian melanoma cases differ in characteristics from Caucasians, such as predominance of the acral lentiginous subtype and low BRAF mutation prevalence." (PMID 32188503, 2020). "We focused our attention on the EGFR gene for NSCLC samples, KRAS, and BRAF genes for mCRC samples, and the BRAF gene for melanoma samples, because target therapy for the mutation of these genes can be prescribed by clinicians." (PMID 32054005, 2020). "MEK inhibitors, such as trametinib, have been approved for the treatment of advanced melanoma patients carrying the BRAF mutation." (PMID 32021565, 2020). "One phase I study reported preliminary clinical activity and a tolerable safety profile for an anti-PD-L1 antibody in combination with dabrafenib (BRAF inhibitor) and trametinib (MEK inhibitor) in BRAF-mutated melanoma as well as in BRAF wild-type melanoma." (PMID 32260561, 2020). "Loss of a functional PTEN gene is observed in 10–35% percent of melanoma cases and is one of the most common causes of resistance to BRAF inhibitors." (PMID 32605090, 2020). "In COMBI-MB, a phase II study, 125 BRAF V600-mutated melanoma patients with BM were divided into four cohorts and treated with dabrafenib plus trametinib." (PMID 32760738, 2020). "BRAF mutations induce melanoma cell proliferation, mitochondrial alterations and fragmentation, and consequently the metabolic switch from OXPHOS toward glycolysis." (PMID 32528879, 2020). "In 2012, the FDA approved trametinib for mutated BRAF melanoma, based on the improved patient survival in the trametinib arm, compared to the standard of care." (PMID 33256089, 2020). "Nonetheless, the converging results obtained by OTX-008 treatment and Gal-1 knockdown with siRNA lead to the solid conclusion that Gal-1 is pivotally implicated in melanoma cell resistance to BRAF-targeted therapy." (PMID 32784465, 2020). "A single-arm, open-label, proof-of-concept study is underway in the Netherlands to investigate the effect of the HDAC inhibitor vorinostat in patients with BRAF V600E-mutated resistant melanoma (NCT02836548)." (PMID 33003483, 2020). "In a retrospective analysis, 12 patients with BRAF V600E mutated melanoma brain metastases were treated with Vemurafenib and radiotherapy (six patients received SRS, six patients received WBRT)." (PMID 32575838, 2020). "In this work, we evaluated the therapeutic potency and molecular mechanism of a novel Hsp90/PI3K inhibitor, DHP1808, in BRAF V600E-mutated A375 melanoma cells." (PMID 32156008, 2020). "One example of lipid metabolism adaptive changes under drug exposure is the BRAF mutated melanoma tolerant to MAPK inhibitors." (PMID 33339398, 2020). "Melanomas with activation of the mutated BRAF have suppressed levels of MITF and PGC1α and decreased oxidative metabolism." (PMID 33091721, 2020). "For example, oncogenic BRAF V600E mutation in melanoma cells fosters tumor immune escape by modulating cell immunogenicity and microenvironment composition." (PMID 32330348, 2020). "In melanoma, myeloma, and colorectal cancer, patients with BRAF mutations at residue D594 have a better prognosis and longer overall survival than those with the V600E mutation." (PMID 33198372, 2020). "An estimated 42–45% of melanomas harbor mutations of the gene for v-Raf murine sarcoma viral oncogene homolog B (BRAF), an activating serine/threonine protein kinase in the mitogen-activated protein kinase (MAPK) signaling pathway." (PMID 33003483, 2020). "The V600E BRAF mutation is also associated with more aggressive tumor features and reduced survival in melanoma patients." (PMID 32610527, 2020). "Here, we present a new mechanism of targeted therapy resistance in melanoma where the treatment with the BRAF inhibitor vemurafenib causes an increased activation of HER3 via shed ligands." (PMID 33327495, 2020).
melanoma (continued). "The dysregulation of RAS/MAPK and PI3K/AKT with BRAF mutations in 60% of patients showed that these pathways are key drivers of melanoma development and progression." (PMID 32021565, 2020). "Targeted therapies in melanoma patients aimed at mutation such as BRAF inhibitors (50% of malignant melanomas) and MEK inhibitors have also been studied extensively." (PMID 32733787, 2020). "It has been recently reported that the occurrence of BRAF mutation is associated to an increased pDC infiltration compared with BRAF-wild type melanomas." (PMID 32054102, 2020). "The first three include melanomas harboring BRAF, NRAS, or neurofibromin 1 (NF1) mutations, respectively, and show constitutive activation of the MAPK pathway." (PMID 32466585, 2020). "NCT02967692 is a phase III study evaluating the safety and efficacy of the combination spartalizumab (anti-PD-1 antibody), dabrafenib (BRAF inhibitor), and trametinib (MEK inhibitor) in patients with unresectable or metastatic BRAF V600-mutated melanoma." (PMID 32260561, 2020). "A close link between these two signaling pathways in BRAF mutated melanoma cells was also shown in a study that analyzed intrinsic cross-resistance to inhibitors of the two pathways." (PMID 32531927, 2020). "In this review, we will retrace the development of molecular-target drugs and the current therapeutic scenario for patients with BRAF mutated melanoma, from the introduction of BRAF inhibitors as single agents to modern clinical practice." (PMID 32760738, 2020). "Although 20 individual BRAF mutations have been described, approximately 90% of BRAF-mutant melanomas present a mutation leading to the substitution of the valine 600 residue by glutamic acid (V600E)." (PMID 33036192, 2020). "A further study showed that baseline ctDNA detection was associated with poor prognosis in metastatic BRAF or NRAS-mutated melanoma patients." (PMID 33255267, 2020). "BRAF mutations occur in 40–50% of melanoma patients, whereas NRAS mutations are identified in additional 15–20%." (PMID 32330348, 2020). "In melanoma, the mutation of the BRAF gene has primary importance, since mutations at the codon 600 are druggable and clinically associated with significant responses." (PMID 33193402, 2020). "In BRAF-mutated human M21 melanoma cells, radiation induced B7-H3 level but there was limited modulation of CSPG4." (PMID 32894202, 2020). "In melanoma, particularly in the BRAF mutated tumors, PERK is particularly important and serves oncogenic properties indicating its constitutive activation." (PMID 31838577, 2020). "BRAF is activated by somatic point mutation in human cancer (mutation in 66% of malignant melanoma)." (PMID 32059541, 2020). "For Mel models, we used BRAF cell lines with Val600Glu mutation that is found in approximately 40%–60% of resistant melanoma in the Caucasian population and is the target of the main chemotherapeutic treatments." (PMID 33260400, 2020). "We will also discuss the resistance mechanisms identified so far, and the future therapeutic perspectives in BRAF mutated melanoma." (PMID 32760738, 2020). "About 90% of melanomas harbor BRAF V600E mutation, which leads to the constitutive activation of RAS/MAPK signaling pathway and malignant cell proliferation." (PMID 32900991, 2020). "At the cellular level, BRAF mutations drive oncogenic behavior of melanoma cells, leading to unrestricted cell growth, increased cell survival, and local invasion through activation of the mitogen-activated protein kinase (MAPK) pathway." (PMID 32313236, 2020). "BRAF mutations, with BRAF V600E being the most prominent, are highly prevalent in both melanoma and colorectal cancers." (PMID 32514188, 2020). "The BRAF V600 mutation leads to the constitutive activation of the MAPK pathway in more than 50% of patients with melanoma." (PMID 32260561, 2020). "Analysis of NRAS and BRAF mutations in stage IV melanoma patients by single reaction ddPCR has shown an overall detection rate of 73%." (PMID 32785074, 2020).
melanoma (continued). "One of the most frequently mutated genes in melanoma is BRAF encoding a protein kinase in the RAS signaling pathway." (PMID 34589668, 2020). "BRAF mutation is involved in various mechanisms of melanoma progression but predominantly hyperactivates downstream MEK/ERK pathway." (PMID 32477956, 2020). "With ICI, the response rate to first or second-line anti-PD1 in BRAF-mutated or wild-type (WT) melanomas ranged from 42% to 45%, with a median PFS of 8.4 to 9.7 and 6.9 months with pembrolizumab and nivolumab, respectively." (PMID 32585901, 2020). "The NRAS was the first oncogene identified in melanoma in 1984, and the second most prevalent after BRAF (mutation frequency of 30%)." (PMID 32850962, 2020). "The most common genetic drivers of melanoma are BRAF-activating mutations such as V600E, often found in conjunction with loss of tumor suppressors such as PTEN3–5." (PMID 32686704, 2020). "Two meta-analyses published in 2011 and 2015 found that those patients with melanoma present a double risk of presenting BRAF mutations compared to patients with chronic sun exposure." (PMID 32775409, 2020). "This mutation class is highly relevant to melanoma, because these tandem substitutions are responsible for the oncogenic BRAF V600R and V600K mutations." (PMID 33207206, 2020). "It is rare, then, that a single kinase is commonly mutated (with the well-known exception, BRAF, which is mutated in over 60% of melanoma cases), suggesting that several infrequently mutated kinases most likely contribute to tumorigenesis and progression." (PMID 33205077, 2020). "We aimed at analyzing the heterogeneity of mutational load of BRAF V600E in biopsies of melanoma patients of different stages, and investigating its potential as a prognosis factor." (PMID 32168325, 2020). "RAS and RAF mutations are implicated in a great portion of malignancies: BRAF V600 mutation is found in 40–60% of melanomas and 10–12% of metastatic colorectal cancer (mCRC), KRAS or NRAS in 55% of mCRC, and KRAS in 20–30% of lung adenocarcinoma." (PMID 33109256, 2020). "A recent study has shown more specific in melanoma cell lines presenting BRAF mutation that their metabolic profiles influences the resistance to a BRAF inhibitor, Vemurafenib." (PMID 32509589, 2020). "Trametinib is currently approved for cases of metastatic, unresectable melanomas harbouring the BRAF‐V600E/K mutation and can be combined with dabrafenib to improve its therapeutic efficacy." (PMID 32352219, 2020). "The present study is the first that shows the capacity of specific Mcl-1 protein inhibitor – MIM1 to induce apoptosis in the amelanotic melanoma cells with BRAF V600E mutation and to intensify the proapoptotic properties of DTIC." (PMID 31432325, 2020). "Concerning treatment, in vitro studies have shown that melanoma cell lines harboring the RAC1 P29S mutation are resistant to BRAF and MEK inhibitors, but its role in conferring this resistance is still to be elucidated." (PMID 32850962, 2020). "BRAF mutations have been detected in about 50% of cutaneous MM cases and to a lesser extent in other melanoma subtypes." (PMID 33142971, 2020). "As BRAFV600E is the most frequent mutation in melanoma, and BRAF and RAS oncogenes were described as potential inducers of NRF2, we tested the effect of BRAFV600E expression on NRF2 in melanocytes." (PMID 32978520, 2020). "According to the literature, melanoma, a malignant cancer, frequently harbors the BRAF p.Val600Glu mutation." (PMID 32847629, 2020). "Using melanoma caused by BRAF gene mutation as an example, we verified the feasibility of this model using the FDA’s drug labels and relevant linked data." (PMID 33084582, 2020). "In patients with BRAFV600-mutated melanoma, BRAF and MEK inhibitors yield very high initial responses." (PMID 32258034, 2020). "In melanoma,BRAF inhibition induces a paradoxical activation of the MAPK/ERK pathway inBRAF wild-type melanoma-associated fibroblasts." (PMID 32595946, 2020).